IDH1 (isocitrate dehydrogenase (NADP(+)) 1)
Diseases named in the same sentence as IDH1 in open-access papers (continued):
Sharing a sentence is not in itself a finding about the gene and the disease.
brain tumors (continued). "IDH1R132H mutation was statistically related to WHO grade in primary tumors, 85.7% of IDH1 mutated tumors were classified as grade II (p < .001), being R132H mutation, significantly more frequent in low grades of primary brain tumors (p = .042) (data not shown)." (PMID 28948065, 2017). "This same hypothesis can also explain why these IDH1 R132 or IDH2 R172 mutations have not been discovered in any non-glial subtype brain tumors." (PMID 28785398, 2017). "It will be important to test whether hypermethylation of these genes is related to other alterations such as IDH1 mutations and EGFR amplification found in brain tumors, Further studies will help clarify the usefulness of these alterations for detecting and managing patients with poor prognosis." (PMID 25621889, 2015). "Histological and immunohistochemical analyses were necessary to verify the histological diagnosis of GBM in contrast to other brain tumors and determine its type (IDH1+, IDH1−)." (PMID 40426873, 2025). "GBMs exhibiting a molecular profile with unmutated IDH1 and an unmethylated MGMT gene promoter tend to recur in most cases, contributing to the poor prognosis of this brain tumor." (PMID 37630276, 2023). "The two-3D stochastic microsensors proposed for the molecular recognition of IDH1 and IDH2 were reliably used for screening tests of biological samples such as brain tumor tissue samples and whole blood samples." (PMID 35159804, 2022). "Exon 4 of IDH1 and IDH2 was analyzed in a series of brain tumors classified according to current WHO criteria." (PMID 29535392, 2018). "For both the IDH1 R132H mutant BT142 and GB10 models described herein, MRK-A was able to achieve robust intracranial 2-HG inhibition in the orthotopic mouse brain tumor setting." (PMID 29062039, 2017). "Patients with wild-type IDH1 brain tumors and high PDPN expression showed a significantly increased VTE risk compared with those with mutant IDH1 tumors and no PDPN expression." (PMID 39682237, 2024). "The frequency of mutations in the genes is consistent with that reported in the literature for IDH1 and IDH2 in brain tumors, EGFR and KRAS in NSCLCs, KRAS and NRAS in CRCs, BRAF, RAS, PIK3CA, and TERT in thyroid nodules, BRAF, NRAS and cKIT in melanoma, and KRAS in pancreatic pre-operative samples." (PMID 32340363, 2020). "Encouragingly, there is evidence to suggest that reducing IDH1 expression may sensitise GBM cells to radiotherapy, a core clinical treatment for paediatric brain tumours." (PMID 33053751, 2020). "IDH1 and VEGF +936 C/T univariate analysis of OS in the 80 patients with brain tumors." (PMID 28948065, 2017). "Among these patients, 98.4% had a unique molecular profile, and aside from three primary brain tumor patients with a single genetic lesion (IDH1 R132H), no two patients within a given histology were molecularly identical." (PMID 26418953, 2015). "Of note, the IDH1 mutation status was not used as a predefined matching criterium for our study, and the higher number of IDH positive brain tumours in the control group (3 patients, vs. 0 in the VTE group) might have had an influence." (PMID 38613361, 2024).
leukemia (119 papers, 2012 to 2026). A malignant (clonal) hematologic disorder, involving hematopoietic stem cells and characterized by the presence of primitive or atypical myeloid or lymphoid cells in the bone marrow and the blood. "Nevertheless, Idh1 was found to be mutated in murine leukemia dormant cells, and a mutated IDH1 gene is frequently observed in human AML at both diagnosis and MRD stages." (PMID 39223638, 2024). "R-2-hydroxyglutarate (R-2HG), a product of mutated isocitrate dehydrogenase 1/2 (IDH1/2), plays an anti-tumor role in leukemia by inhibiting cell proliferation, promoting cell cycle arrest, and apoptosis." (PMID 39473440, 2024). "Leukemia-associated IDH1/2 mutations induce a neomorphic enzymatic function that converts α-ketoglutarate to 2-hydroxyglutarate." (PMID 37612540, 2023). "IDH1 R132 hotspot mutations are particularly frequent in leukemia, primary malignant brain tumors and intrahepatic cholangiocarcinomas (iCCA)." (PMID 38086797, 2023). "The effects of D-2-HG have been extensively studied in the setting of leukemia because of its accumulation in patients with IDH1/2 mutations." (PMID 37742191, 2023). "Inhibition of IDH1 in leukemia using wild-type IDH1 inhibitors causes a shift in cellular metabolism from oxidative phosphorylation to glycolysis, promoting the Warburg effect, a well-known feature of rapidly proliferating cells in mammals." (PMID 36497259, 2022). "BAY1436032 is an allosteric inhibitor targeting all IDH1 mutations, which inhibits cell proliferation and self-renewal of leukemia stem cells." (PMID 35740380, 2022). "Numerous new emerging reports of exome sequencing have identified frequent mutations in the IDH1 enzyme or its homolog IDH2 in leukemia and other cancers." (PMID 35743098, 2022). "In PV patients, the presence of ASXL1, SRSF2, and IDH1 seems to be associated with poorer overall survival and leukemia-free survival." (PMID 35562964, 2022). "In fact, it was recently reported that the synergistic activity of the IDH1 inhibitor BAY1436032 with AZA in AML with IDH1 mutations enhances anti-leukemia activity by co-targeting metabolism and methylation." (PMID 33808599, 2021). "Specifically, one group has recently demonstrated that the IDH1 R132H mutation sensitizes leukemia cells to the cytotoxic effect of the selective Bcl-2 inhibitor ABT199." (PMID 34209035, 2021). "As expected, tumours with a high frequency of IDH1/2 mutations include the central nervous system (CNS), biliary tract, bone, haematopoietic and lymphoid tumours (leukemias)." (PMID 33740099, 2021). "Several studieshave been performed on mouse and cell models of leukemia caused by mutations inthe TET2 or IDH1 gene." (PMID 33456974, 2020). "Apart from the NUP98 fusions, Hox gene dysregulation has also been associated with MLL fusions, the CALM-AF10 fusion, and NPM1 and IDH1 mutations in leukemia." (PMID 32993115, 2020). "The following studies performed by other groups have further revealed that mutations in IDH1 are associated with leukemia, colon cancer and prostate cancer." (PMID 32373065, 2020). "As well as malignancies of the central nervous system and leukaemia, mutations of IDH1 have been discovered in other solid cancers with low incidence." (PMID 30305430, 2018). "Multiple studies have shown that IDH1/IDH2 mutations present in leukemia cause the accumulation of 2HG, inhibiting DNA demethylation and producing a hypermethylation phenotype." (PMID 29922517, 2018). "Polymerase chain reaction (PCR) and direct sequencing were performed on exon 4 of IDH1/2 genes and mutation status was correlated with overall survival (OS) and leukemia-free survival (LFS)." (PMID 24936872, 2014). "That is, the presence of IDH1/2 mutations negatively impacts leukemia-free survival in PMF." (PMID 38600315, 2024).
leukemia (continued). "In another recent high-profile paper, it was shown that IDH1 mutation in leukemia cells caused MAPK activation, and targeting this pathway through CDK4/6 inhibitor Abemaciclib, more effectively inhibited proliferation in IDH mutant AML than in IDH wild-type AML." (PMID 38086797, 2023). "Importantly, in this case report, two R/R AML patients with initial IDH1-R132C mutation achieved durable remissions with therapy of ivosidenib, but leukemia cells recurred with emergence of neomorphic mutation IDH2-R140Q." (PMID 35814406, 2022). "In addition, leukemia cells from AML patients with IDH1/2 mutations exhibited DNA hypermethylation patterns at global and specific gene levels." (PMID 34436421, 2021). "Somatic mutations of several epigenetic modulators (DNMT3A, TET2, IDH1/2) occur frequently among patients with pre-leukemia diseases such as MDS and apparently healthy individuals with clonal hematopoiesis or CHIP, an aging-related phenotype associated with increased risk of AML." (PMID 29075615, 2017). "This Registered Report describes the proposed replication plan of key experiments from “The common feature of leukemia-associated IDH1 and IDH2 mutations is a neomorphic enzyme activity converting alpha-ketoglutarate to 2-hydroxyglutarate” by Ward and colleagues, published in Cancer Cell in 2010." (PMID 26943899, 2016). "Previously, homozygous IDH1 mutations have been detected in leukemia and thyroid cancer patients." (PMID 24868540, 2014). "The reduced frequency of recurrent chromosomal aberrations and other AML-associated mutations in IDH1/2-mutant leukemias implies that mutations in IDH1/2 may represent a distinct mechanism for AML pathogenesis." (PMID 24202321, 2013). "In the Mayo Clinic group, leukemia-free survival was associated with IDH1 and SRSF2 mutations." (PMID 37745842, 2023). "Additionally, the enrichment of FLT3-like leukemias in IDH1 mutations (which are correlated with NPM1 mutation) could set the basis for the development of new clinical trials testing the combination of different check-point inhibitors in AML." (PMID 33592069, 2021). "In the CTRL-ROY group, enrichment was significant for “leukemia” and “acute leukemia” terms (NES = 2.12, Q = 0.03), driven by key myeloid malignancy-associated genes DNMT3A, IDH1, SRSF2, and TET2." (PMID 41371958, 2026). "In IDH1-mutant xenograft tumor models, olutasidenib potently suppressed 2-HG production and induced differentiation of leukemia cells." (PMID 38600315, 2024). "Individual risk stratification by molecular profiling of leukemia samples and availability of many effective agents for molecular subtypes, e.g., FLT3 inhibitors or IDH1/2 inhibitors, allow the first steps towards personalized AML therapy." (PMID 35406464, 2022). "IDH1 and IDH2 mutations then cause a hypermethylation phenotype in leukaemia and inhibit haematopoietic stem cell differentiation." (PMID 34617422, 2022). "This work shows that the treatment of wild-type IDH1 leukemia cells with a specific IDH1 inhibitor shifted leukemic cells toward glycolysis from the oxidative phosphorylation (OXPHOS) phenotype." (PMID 35743098, 2022). "The results showed that targeting wild-type IDH1 inhibition shifted leukemia cell metabolism toward oxidative phosphorylation from glycolysis, enhanced ROS, and deregulated membrane potential, leading to cell death." (PMID 35743098, 2022). "Similar to IDH1/2 mutations, mutations in and the promoter hypermethylation of TET2 have been confirmed in leukaemias, myelodysplastic syndrome, myeloproliferative neoplasms and low-grade diffuse gliomas." (PMID 34905094, 2022). "In efforts to develop in vivo models for IDH1/2 leukemia, several investigators have developed genetically engineered mice that express mutant forms of Idh1 or Idh2." (PMID 36330381, 2022).
leukemia (continued). "In leukemia, the IDH1/IDH2 gene restructures the enzyme for isocitrate while increasing the affinity for α-ketoglutarate (αKG) with the production of 2HG." (PMID 35743098, 2022). "Male IDH1 and IDH2 mutations and marrow blasts ≥5% were independent risk factors for worse leukemia free survival (LFS) (p < 0.05)." (PMID 33609081, 2021). "One of the key mRNA targets whose methylation changed upon R-2HG administration in IDH1 or 2 wild type leukemia cells was the MYC one, thus made less stable, with a consequent reduction of Myc expression and signalling." (PMID 32316617, 2020). "Mutant IDH1 alone was unable to transform hematopoietic cells, but consistently accelerated leukemia development induced by HoxA9." (PMID 32859092, 2020). "IDH1/2 mutations were identified in about a fifth of AML patients, contributing to leukemia by blocking differentiation of hematopoietic cells." (PMID 32245484, 2020). "The successful development of effective targeted therapies for IDH1- and IDH2-mutant AMLs has led to the regulatory approval of IDH1 and IDH2 inhibitors, improving response rates and outcomes for patients whose leukemia harbors these mutations." (PMID 32859092, 2020). "This NUP98-NSD1-positive PDX model was analyzed in the 6th transplantation and showed AML with normal karyotype, while it was wildtype for genes frequently mutated in leukemia, such as FLT3, NRAS, NPM1, IDH1/2, and DNMT3A." (PMID 32993115, 2020). "Other studies have supported a role of Meis1 and HoxA9 in cooperation with IDH1 or IDH2 mutant to drive leukemia development in mouse models." (PMID 32859092, 2020). "Several studies have provided evidence for the adverse impact of somatic mutations in ASXL1, EZH2, IDH1/2, and SRSF2 on shorter OS or leukemia-free survival in patients with PMF." (PMID 32781570, 2020). "The group of AMLs bearing IDH1 or IDH2 mutations is heterogeneous and a better definition of biologically and clinically relevant subgroups among these leukemias is very important to better define the spectrum of sensitivity to IDH-targeted therapies." (PMID 30813354, 2019). "The pan-mutant IDH1 inhibitor affected leukemia stem cells’ ability to self-renew with downregulation of stemness-associated genes and upregulation of those associated with myeloid differentiation." (PMID 30857299, 2019). "Of note, patients with concurrent JAK2 and IDH1/2 mutations have shorter leukemia-free survival, suggesting that comutations in JAK2 and in IDH1/2 can promote MPN progression and transformation." (PMID 29355841, 2018). "We extensively validate a SL interaction identified by MiSL between the IDH1 mutation and ACACA in leukaemia using gene targeting and patient-derived xenografts." (PMID 28561042, 2017). "Novel drugs targeting mutant IDH1/2, for example, are already undergoing phase II/III trials with treatment of advanced leukemia harboring these mutations." (PMID 28092669, 2017). "It has also been shown that neomorphic IDH1 and 2, as well as loss of function mutations in TET2 establish a hypermethylation phenotype in leukemia." (PMID 28785398, 2017). "Screening of leukemia-initiating mutations, such as DNMT3A, NPM1 or IDH1/2 mutations should be performed at diagnosis but only NPM1 and IDH1/2 are robust target for MRD monitoring." (PMID 26486081, 2015). "Compared to current targeted therapies, which often address single genetic mutations (e.g., FLT3, IDH1/2), the multi-targeted nature of YWLS-derived compounds offers broader anti-leukemia effects and may overcome the limitation of clonal heterogeneity." (PMID 40520175, 2025). "Similarly, IDH1 and IDH2 gain-of-function mutations in leukemia lead to the accumulation of the competitive inhibitor of TET enzymes, 2-hydroxyglutarate (2-HG), with consequent DNA hypermethylation." (PMID 41516186, 2025).
leukemia (continued). "However, loss-of-function TET2 variants are common in clonal hematopoiesis and predominate in AML of older adults, while IDH1/2 mutations are uncommon in CHIP, yet when such clones do arise they carry a markedly elevated risk of progression to overt leukemia." (PMID 40651916, 2025). "Conversely, we found that FLT3-ITD and IDH1 mutations were more frequent at R/R, supporting the idea that these leukemias could be more resistant (although the prognostic impact of IDH1 remains controversial)." (PMID 40075701, 2025). "Ivosidenib and enasidenib specifically inhibit the activity of mutated IDH1 and IDH2 enzymes respectively to lower the 2-HG levels, which helps to restore the differentiation process of cells and reduces the malignant proliferation of leukemia cells." (PMID 39575391, 2024). "More precisely, targeting a single mutation (as tyrosine kinase inhibitors for BCR::ABL1 fusion gene, FLT3 or IDH1/2 mutations) is not the “magic bullet” since leukemia heterogeneity will allow tumor escape via clonal drift under chemotherapy pressure." (PMID 37444390, 2023). "Since the wild-type IDH1 enzyme is a crucial metabolic enzyme, in this study, we aimed to understand the metabolic impact of targeting wild-type IDH1 using GSK864 (an IDH1 mutant inhibitor that also inhibits wild-type IDH1 at high concentrations) in leukemia cell types as an experimental model." (PMID 35743098, 2022). "Mutations in IDH1 and IDH2 were recognized as independent factors for leukemia transformation." (PMID 33609081, 2021). "Therefore, despite the limitation of using a small sample size, our study has critically compared IDH1/2 alterations in leukemia patients in one region." (PMID 34946913, 2021). "Additionally, a relative enrichment in IDH1 mutants within FLT3-like leukemias was detected in the discovery set GSE14468 (p-value 2.07 x 10−4)." (PMID 33592069, 2021). "Given that JAK2/IDH-mutated mice do not develop overt leukemia, it is possible that IDH1/IDH2 are not key-genes in leukemic transformation but rather SRSF2 is." (PMID 34771693, 2021). "Theeffect of ASC addition was also tested on IDH1 mutant mouse leukemia cells." (PMID 33456974, 2020). "Finally, in the middle of 2018, ivosidenib (AG-120), the first IDH1 inhibitor, was introduced to treat leukemia and cholangiocarcinoma." (PMID 32110969, 2020). "Given the promising results in murine leukemia models with co-occurring mutations, we then evaluated the ex vivo activity of TP-0903 and TKIs in human primary samples with coexisting recurrent mutations (e.g., FLT3-ITD, IDH1/2, ASXL1, DNMT3A, NPM1, and SRSF2)." (PMID 33268594, 2020). "In multivariate analysis, IDH1 mutations but not IDH2 mutations were associated with shortened leukemia-free survival." (PMID 32859092, 2020). "Two DNA demethylating agents, 5-azacitidine and decitabine, have already been used for different AML subtypes and could be of interest in IDH1/2-mutant leukemia." (PMID 28471392, 2017). "In order to compare the ability of mIDH1 inhibitors to induce differentiation of AML cells, we implemented a cell differentiation assay using human THP1 leukemia cells engineered to express either wild type IDH1 (THP1-WT) or mIDH1-R132H (THP1-R132H) under a doxycycline-inducible promoter." (PMID 28986582, 2017). "Mutations in IDH1 and IDH2 that result in a new enzymatic activity may represent novel, tractable targets for this genetically defined subset of leukemia patients." (PMID 23938080, 2013). "In general, these mice did not develop leukemia, suggesting that additional, complementary mutations may be required for oncogenic transformation initiated by an Idh1/2 mutation." (PMID 36330381, 2022). "Some therapeutically-targetable leukemia antigens originate from oncogenesis itself and are leukemia cell-specific, such as the BCR/ABL1 fusion protein in CML and Philadelphia (Ph)+ ALL, PML/RAR-α in acute promyelocytic leukemia, FLT3-ITD and mutated NPM1 in AML and IDH1/2." (PMID 29466292, 2018).